KIF5A (kinesin family member 5A)
Description:
Microtubule-dependent motor required for slow axonal transport of neurofilament proteins (NFH, NFM and NFL). Can induce formation of neurite-like membrane protrusions in non-neuronal cells in a ZFYVE27-dependent manner. The ZFYVE27-KIF5A complex contributes to the vesicular transport of VAPA, VAPB, SURF4, RAB11A, RAB11B and RTN3 proteins in neurons. Required for anterograde axonal transportation of MAPK8IP3/JIP3 which is essential for MAPK8IP3/JIP3 function in axon elongation.
Synonyms: NKHC; D12S1889; MY050; ALS25; NEIMY; SPG10
Tractability: Small molecule: a structure with a bound ligand is known. Antibody: the Human Protein Atlas places it where antibodies can reach. PROTAC: ubiquitination databases record sites on it; its protein half-life has been measured.
Target class: Other cytosolic protein
Gene: Protein-coding gene on chromosome 12 (57,546,026 to 57,586,633, forward strand). Ensembl gene ENSG00000155980.
Subcellular location: Cytoplasm, perinuclear region; Cytoplasm, cytoskeleton; Perikaryon
Subcellular location (Human Protein Atlas): Cytosol; Nucleoplasm; Mid piece; Mitotic spindle; Plasma membrane; Principal piece
Pathways (Reactome):
Hemostasis: Kinesins
Immune System: MHC class II antigen presentation
Metabolism of proteins: Insulin processing
Signal Transduction: RHO GTPases activate KTN1
Vesicle-mediated transport: COPI-dependent Golgi-to-ER retrograde traffic
Gene Ontology:
Molecular function: microtubule motor activity; protein binding; cytoskeletal motor activity; plus-end-directed microtubule motor activity; ATP binding; kinesin binding; microtubule binding
Biological process: anterograde axonal protein transport; anterograde dendritic transport of neurotransmitter receptor complex; axon guidance; chemical synaptic transmission; microtubule-based movement; retrograde neuronal dense core vesicle transport; synaptic vesicle transport; vesicle-mediated transport
Cellular component: membrane; cytosol; kinesin complex; perikaryon; axon cytoplasm; ciliary rootlet; cytoplasm; cytoskeleton; dendrite cytoplasm; neuron projection; neuronal cell body; perinuclear region of cytoplasm; postsynaptic cytosol
Genetic constraint (gnomAD): Loss-of-function variants: 32 observed, 136.53 expected, observed/expected ratio (o/e) 0.23, 90% interval 0.18 to 0.31. The upper end of that interval is the gene's LOEUF score, 0.31, which puts it in group 1 of 6, group 1 being the genes least tolerant of losing a copy. Missense variants: 840 observed, 1,345.9 expected, observed/expected ratio (o/e) 0.62, 90% interval 0.59 to 0.66. Synonymous variants: 442 observed, 521.66 expected, observed/expected ratio (o/e) 0.85, 90% interval 0.78 to 0.92.
Gene-disease validity (ClinGen):
ClinGen rates the evidence that KIF5A causes each of these diseases.
inherited neurodegenerative disorder (autosomal dominant): Definitive. An inherited disorder characterized by progressive degeneration and atrophy of the nervous system.
Homologues: Orthologues: macaque KIF5A (100% identical), chimpanzee KIF5A (99% identical), dog KIF5A (99% identical), pig KIF5A (99% identical), guinea pig KIF5A (99% identical), rabbit KIF5A (99% identical), mouse Kif5a (98% identical), rat Kif5a (97% identical), tropical clawed frog kif5a (88% identical), zebrafish kif5aa (72% identical). Paralogues in human: KIF5C (70% identical), KIF5B (66% identical), KIF21A (25% identical), CENPE (25% identical), KIF21B (24% identical), KIF7 (24% identical), KIF27 (23% identical), KIF4A (23% identical), KIF4B (23% identical), KIF15 (23% identical), KIF11 (22% identical), KIF13B (22% identical), and 29 more.
Diseases named in the same sentence as KIF5A in open-access papers:
KIF5A is named in the same sentence as 78 diseases in open-access papers, as found by Europe PMC text mining. Sharing a sentence is not in itself a finding about the gene and the disease. The quoted sentences say what the papers report.
hereditary spastic paraplegia (40 papers, 2006 to 2025). Hereditary spastic paraplegias (HSP) comprise a genetically and clinically heterogeneous group of neurodegenerative disorders characterized by progressive spasticity and hyperreflexia of the lower limbs. "Mutations in KIF5A have been identified as the cause of a kind of hereditary spastic paraplegia in humans." (PMID 39507380, 2024). "For example, mutations in the KHC gene KIF5A cause inherited neuropathies, hereditary spastic paraplegia, and amyotrophic lateral sclerosis (ALS)." (PMID 37259916, 2023). "Charcot-Marie-Tooth disease type 2A can be caused by mutations in Kif1b, congenital fibrosis of the extraocular muscles can be caused by mutations in Kif21a, and a loss-of-function mutation in Kif5a motor domain can result in hereditary spastic paraplegia." (PMID 35259089, 2022). "In humans, a missense mutation within the KIF5A gene (N256S) causes an autosomal dominant form of hereditary spastic paraplegia, known as SPG10." (PMID 33484325, 2021). "Hereditary spastic paraplegia (HSPs) is caused by mutations in the kinesin-1 heavy chain subunit KIF5A." (PMID 27213408, 2016). "KIF5A is expressed exclusively in neurons, and has been recently linked to hereditary spastic paraplegias (HSPs), a genetically heterogeneous group of neurodegenerative disorders characterized by progressive lower-limb spasticity and weakness." (PMID 24742296, 2014). "Furthermore, transcripts of disease-associated genes, such as BSCL2-206, REEP1-201, UCHL1-207/209 and KIF5A-202, all associated with hereditary spastic paraplegia (HSP), were significantly differentially expressed." (PMID 40735840, 2025). "As mutations of the kinesin-1-encoding gene KIF5A were linked to manifestation of familial hereditary spastic paraplegia, it can be assumed that altered interactions of BICD2 with kinesin 1 are resulting in a different pathophysiology that is associated with HSP." (PMID 37047781, 2023). "Motor or stalk domain mutations in KIF5A cause hereditary spastic paraplegia, and tail domain mutations in KIF5A cause ALS17,18,92, which may be explained by disrupted auto-inhibition." (PMID 37296096, 2023). "For KIF1A and KIF5A, mutations causing hereditary spastic paraplegia – associated with the dysfunction and degeneration of upper motor neurons – and amyotrophic lateral sclerosis alter the function of kinesins, motor proteins that shepherd vesicles up and down the microtubular routes along the axon." (PMID 34897416, 2021). "Moreover, kif5a mutations are associated with the development of hereditary spastic paraplegia (SPG10), a neurodegenerative disease." (PMID 25274010, 2014). "Mutations in the gene encoding KIF5A (kinesin 5A), a neuron-specific anterograde molecular motor protein, are causative for hereditary spastic paraplegia (HSP), Charcot-Marie-Tooth disease type 2 (CMT2) and ALS." (PMID 40395983, 2025). "Hereditary Spastic Paraplegia (HSP) is caused by mutations in the KIF5A N-terminal motor domain." (PMID 40589526, 2025). "The axonal transport of mitochondria in zebrafish peripheral sensory neurons depends exclusively upon KIF5A, and only KIF5A dysfunction leads to seizure and Hereditary Spastic Paraplegia." (PMID 39651860, 2025). "For example, mutations in the N-terminal motor domain of KIF5A are responsible for hereditary spastic paraplegia (SPG10 MIM 604187) and CMT type 2 (CMT2), clustered in the switch regions SWI and SWII necessary for microtubules interaction." (PMID 34354735, 2021). "The most common disease associated with KIF5A mutations is spastic paraplegia type 10, which may present as uncomplicated HSP (hereditary spastic paraplegia) or less commonly complicated HSP accompanied by various additional neurologic features." (PMID 33810506, 2021). "Here, mutations in the gene coding for the motor protein KIF5A have been linked to Charcot–Marie–Tooth disease type 2D (CMT2D), amyotrophic lateral sclerosis (ALS) and hereditary spastic paraplegia (HSP)." (PMID 32961072, 2020).
hereditary spastic paraplegia (continued). "Of note, there are nine genes among these targets that when mutated are known causes for inherited peripheral neuropathies (IPN) and hereditary spastic paraplegia (HSP) (Inf2, Sox10, Wnk1, Med25, Fa2h, Bscl2, Slc12a6, Kif1a and Kif5a)." (PMID 28077174, 2017). "Mutations in Kif5A, the human ortholog of Drosophila Khc, can cause both Charcot-Marie-Tooth Type 2 disease (CMT2) and the SPG10 form of hereditary spastic paraplegia (HSP)." (PMID 24023935, 2013). "Interestingly, missense mutation in the N-terminal motor domain and the central stalk domain of KIF5A is known to be related to autosomal diseases including hereditary spastic paraplegia and Charcot–Marie–Tooth type 2 (CMT2)." (PMID 38028604, 2023). "Variations in the KIF5A gene that interfere with axonal transport have emerged as a distinguishing feature in several neurodegenerative disorders, including hereditary spastic paraplegia (HSP10), Charcot-Marie-Tooth disease type 2 (CMT2), and Amyotrophic Lateral Sclerosis (ALS)." (PMID 38028604, 2023). "Crucially, it also binds to all KIF5 family members, although the interaction is strongest with KIF5A, which is striking considering both protrudin and KIF5A (but not KIF5B or C) can cause hereditary spastic paraplegia when mutated." (PMID 34571990, 2021). "Variant filtering identified potentially deleterious mutations in three known disease genes: DCTN1, KIF5A and NEFH, which have been all associated with similar clinical presentations of amyotrophic lateral sclerosis, Parkinsonism and/or hereditary spastic paraplegia." (PMID 25957632, 2015). "In addition, mutations in kinesin family member 5A (KIF5A) and SPARTIN, which facilitate endosomal trafficking, are associated with motor neuron dysfunction in hereditary spastic paraplegia." (PMID 26115514, 2015). "Intriguingly, mutations in the kinesin motor domain and coiled-coil domain within the N-terminal part of KIF5A have been reported in Hereditary spastic paraplegia (HSP) and Charcot–Marie–Tooth (CMT) patients." (PMID 30721407, 2019). "Mutations in the KIF5A N-terminal motor domain are known to cause SPG10; An autosomal dominant hereditary spastic paraplegia (HSP), as well as rare Charcot-Marie-Tooth disease 2 (CMT2) cases." (PMID 30583522, 2018). "Mutations in the motor domain of KIF5A, one of the KHC subunits has been shown to cause hereditary spastic paraplegia (HSP)." (PMID 27213408, 2016). "Loss of function of the neuronal Kinesin-1 family member KIF5A is linked to the human neurodegenerative disease Hereditary Spastic Paraplegia (HSP) Type 10 (HSP(SPG10))." (PMID 17009871, 2006). "The pathogenic variants in KIF5A and MYH2 genes are associated with autosomal dominant conditions but not one (hereditary spastic paraplegia or body myopathy type 3) is clinically consistent with symptoms of the patient." (PMID 34439639, 2021). "Similarly, constitutive knockout in mice of KIF5A, the gene responsible for a number of neuromuscular disorders including CMT2, hereditary spastic paraplegia, and amyotrophic lateral sclerosis, results in lethality soon after birth." (PMID 32294113, 2020). "The extensive repertoire of kinesin families, especially the KIF5 family (comprising KIF5A, KIF5B, and KIF5C), stand out as crucial players in anterograde transport, with disruptions leading to neurodegenerative conditions like Alzheimer’s and hereditary spastic paraplegia." (PMID 39507380, 2024).
amyotrophic lateral sclerosis (30 papers, 2011 to 2026). Amyotrophic lateral sclerosis (ALS) is a neurodegenerative disease characterized by progressive muscular paralysis reflecting degeneration of motor neurons in the primary motor cortex, corticospinal tracts, brainstem and spinal cord. "KIF5A is implicated in several diseases, including spastic paraplegia 10, neonatal intractable myoclonus, and amyotrophic lateral sclerosis (ALS)." (PMID 41345834, 2025). "Among them, Kif5a is neuron specific and highly expressed in the central nervous system, and it has been implicated in neurodegenerative diseases such as amyotrophic lateral sclerosis (ALS) and, recently, RGC degeneration after optic nerve injury." (PMID 36862119, 2023). "Recently, a KIF5A (kinesin-1) mutation causing the neurodegenerative disease Amyotrophic Lateral Sclerosis (ALS) has been linked to a loss of autoinhibition." (PMID 36524956, 2023). "This study explored the impact of KIF5A rs113247976 (p.Pro986Leu), a risk allele for amyotrophic lateral sclerosis (ALS), on phenotypic variability in two Italian ALS cohorts (discovery, n = 865; replication, n = 1174)." (PMID 40276954, 2025). "Recent studies showing that amyotrophic lateral sclerosis (ALS)-linked mutations in KIF5A disrupt autoinhibition underscore the broad pathophysiological significance of these questions." (PMID 36112680, 2022). "Interrogation of amyotrophic lateral sclerosis (ALS)-linked GWAS gene networks, astrocyte-based multi-omics datasets and cellular models identifies kinesin motor protein KIF5A as a modifier of astrocyte process integrity and potential target in ALS." (PMID 37386082, 2023). "Fibroblasts from an amyotrophic lateral sclerosis patient with simultaneous mutations in the MATR3 gene and KIF5A gene were isolated and reprogrammed into induced pluripotent stem cells via a non-integrating Sendai viral vector." (PMID 33388707, 2021). "In this cohort is reported a patient carrying a novel familial mutation in the tail domain of KIF5A [a protein domain previously associated with familial amyotrophic lateral sclerosis (ALS)], and a CMT patient carrying a HSPB1 mutation, previously reported in ALS." (PMID 34354735, 2021). "KIF5A mutation causes familial Amyotrophic lateral sclerosis (ALS; OMIM: 05400)." (PMID 35141153, 2021). "Mutations in KIF5A, KIF5B and KIF5C are causes of neurological disorders such as amyotrophic lateral sclerosis (ALS)." (PMID 41290147, 2025). "Mutations in spastin and KIF5A are the primary cause for HSP and mutation in VAP-B causes amyotrophic lateral sclerosis (ALS)." (PMID 22216323, 2011).
Spastic paraplegia (17 papers, 2009 to 2025). Complete loss of the ability to move the lower limbs accompanied by spasticity of the lower limbs. "The KIF5A:c.484C>T (p.Arg162Trp) variant has been reported in a three-generation pedigree with spastic paraplegia as a primary symptom." (PMID 30778698, 2019). "Mutations in KIF5A are associated with spastic paraplegia (SPG10), and can also cause peripheral neuropathy, parkinsonism, retinitis pigmentosa and behavioural problems." (PMID 25957632, 2015). "Dysfunctional KIF5A causes spastic paraplegia (SPG10) with predominant motor neuron affection in humans." (PMID 22466687, 2012). "A heterozygous mutation at the 12q13 kinesin-5A (SPG10/KIF5A) is necessary for moving macromolecules and organelles inside the cells, i.e., axonal transport is linked with AD neurological disorders forms such as spastic paraplegia and peripheral neuropathy." (PMID 35163618, 2022). "Molecular analysis identified a new heterozygous deletion mutation: NM_004984.2:c.[2868_2870delTCT], NP_004975.2:p.(Leu957del), (rs575223790) in KIF5A (MIM 602821) considered as likely pathogenic and thus responsible for spastic paraplegia 10 with neuropathy and autosomal dominant (MIM 604187)." (PMID 34354735, 2021). "Moreover, variants in KIF5A and KIF5C lead to spastic paraplegia (MIM#604187) and cortical dysplasia (MIM#615282), respectively." (PMID 27435318, 2016). "Additionally, the patient Family ID 1141 reported in this paper represents the first case of a familial mutation, the new heterozygous deletion p.Leu957del, falling in the tail domain of KIF5A producing spastic paraplegia 10 with autosomal dominant neuropathy (MIM 604187)." (PMID 34354735, 2021).
Charcot-Marie-Tooth disease type 2 (7 papers, 2013 to 2026). A Charcot-Marie-Tooth disease characterized by abnormalities in the axon of the peripheral nerve cell. "A study performed in 2014 confirmed that KIF5A mutations can involve both the peripheral and central nervous system, resulting in variable phenotypes ranging from HSP to Charcot Marie Tooth Disease type 2." (PMID 26543653, 2015). "Furthermore, it has been discovered that KIF5A mutations can involve both the peripheral and central nervous system, resulting in variable phenotypes ranging from HSP to Charcot Marie Tooth Disease type 2." (PMID 26543653, 2015).
breast cancer (6 papers, 2016 to 2024). A primary or metastatic malignant neoplasm involving the breast. "Many studies have demonstrated that high expression of KIF5A is associated with cancer progression and a poor prognosis, such as in bladder, lung, and breast cancers." (PMID 36675580, 2023). "Recent studies have illustrated that the high expression of KIF5A was related to poor prognosis of solid tumors, including bladder cancer, prostate cancer, and breast cancer." (PMID 36686769, 2022). "Of note, the high expression of KIF5A was related to exacerbated prognosis of solid tumors, including bladder cancer, prostate cancer, and breast cancer." (PMID 36686769, 2022). "Similar results were also previously reported on the association between taxane resistance in basal-like breast cancer and kinesins, including KIF3C, KIF5A and KIF12." (PMID 27128470, 2016). "The high expression of KIF5A is reported to be connected to the dismal prognosis of bladder cancer (BCa), breast cancer (BC), and prostate cancer (PCa)." (PMID 39517115, 2024).
Ataxia (5 papers, 2009 to 2023). Ataxia refers to impaired coordination of voluntary muscle movement. "The second, KIF5A variant c.1402C>T (p.Arg468Trp), which altered the stalk part of the protein, was identified in a female proband with pyramidal signs, ataxia, dysdiachokinesia, bradykinesia, titubation, ophthalmoparesis and dementia, in whom first symptoms appeared after turning." (PMID 30778698, 2019).
multiple sclerosis (5 papers, 2010 to 2023). A progressive autoimmune disorder affecting the central nervous system resulting in demyelination. "Genetic variation in kinesins has also been linked to susceptibility to autoimmunity: specifically, variants in KIF21B and KIF5A have been associated with multiple sclerosis in humans, while variants in KIF1C predispose mice to autoimmune orchitis." (PMID 37895021, 2023). "KIF5A has been associated with rheumatoid arthritis, type-1-diabetes, and is close to a locus recently reported to be associated with multiple sclerosis." (PMID 21152001, 2010). "KIF5A along with other kinesin members including KIF1B and KIF21B were significantly reduced at the mRNA level and KIF5A at the protein level in gray matter of multiple sclerosis (MS) brains." (PMID 33691783, 2021).
Charcot-Marie-Tooth disease (4 papers, 2021 to 2024). An inherited degenerative disorder involving the peripheral nerves. "For instance, the same mutations of the valosin-containing protein (VCP) gene and C9orf 72 appear to be present in individuals with ALS, FTD, and other neurological syndromes, and mutations in kinesin family member 5A (KIF5A) are associated with ALS and the Charcot-Marie-Tooth disease." (PMID 33854469, 2021).
frontotemporal dementia (4 papers, 2009 to 2023). Frontotemporal dementia (FTD) comprises a group of neurodegenerative disorders, characterized by progressive changes in behavior, executive dysfunction and language impairment, as a result of degeneration of the medial prefrontal and frontoinsular cortices. "Importantly, mutations in KIF5A have been identified in ALS, frontotemporal dementia (FTD), hereditary spastic paraplegia and rare cases of CMT disease type 2." (PMID 34789332, 2021).